BDNF (brain derived neurotrophic factor)
Diseases named in the same sentence as BDNF in open-access papers (continued):
Sharing a sentence is not in itself a finding about the gene and the disease.
depression (continued). "Given the mounting evidence that genetic variants such as BDNF Val66Met polymorphism are important stress vulnerability factors sets the stage for future studies that should explore the childhood adversity × stressful life events × BDNF interaction in the context of depression." (PMID 24433458, 2014). "Moreover, in the present study, there was a decrease in the expression of BDNF mRNA in the rat hippocampus as well as an increase in depression- and anxiety-like symptoms following protracted abstinence from repeated morphine administration." (PMID 24527041, 2014). "Interestingly, one recent study reported that serum BDNF increased with 12-week yoga in depression patients." (PMID 25120574, 2014). "As these clinical reports suggest that a possible association between estrogen and dysregulation of the HPG- and HPA-axis in women with depression, the interaction among BDNF, estrogen, HPA axis, and HPG-axis is a critical subject when considering treatment for PPD." (PMID 25309465, 2014). "Serum BDNF, however, has been shown to be decreased by depression and psychosocial stress." (PMID 24586790, 2014). "This neurotrophic hypothesis of depression claims that decreased levels of BDNF contribute to the hippocampal atrophy seen in depressed patients." (PMID 25431319, 2014). "In the present study, we confirmed the antidepressant effects of the swimming protocol, and, as previously reported, the induction of BDNF expression was also found in this study, suggesting the involvement of BDNF in the amelioration of depression by swimming exercise." (PMID 25477997, 2014). "Indeed, BDNF has a well recognized role in the etiology as well as in the treatment response of patients affected by different psychiatric disorders including major depression." (PMID 25565964, 2014). "Moreover, a study using animal models of depression showed that BDNF knock-down in specific sites of the hippocampus resulted in depression-like behavior." (PMID 25505429, 2014). "The results (Experiment 2) confirm the previous reports that chronic corticosterone injections induce depression-like behavior and hippocampal impairment in mice, considering the increased immobility time in behavioral tests and the reduced expression of BDNF and NF-L in the hippocampus." (PMID 24523822, 2014). "Regarding plausible connection between the effect of yoga and circulating BDNF level, only one study showed that, in depression patients, the 12-week yoga intervention increased BDNF along with decreased severity of depression, which is consistent with the results of the present study." (PMID 25120574, 2014). "This suggests that serotonin transporter and BDNF genes may confer sensitivity to early and late environmental factors respectively and play complementary yet distinct roles in the depression aetiology." (PMID 24433458, 2014). "Low levels of BDNF were correlated with clinical severity of depression and mania." (PMID 25202283, 2014). "Several clinical reports have shown depression-induced deregulation of serum BDNF concentration." (PMID 25431319, 2014). "People with depression show diminished levels of BDNF in their serum." (PMID 24999318, 2014). "Furthermore, when exposed to stress, BDNF(±) mice demonstrate an anxiety- and depression-like behavioral phenotype." (PMID 24817844, 2014). "Further, since nutritional status has been shown to affect critical pathways involved in depression through both BDNF function and the monoamine system, we also review current evidence surrounding diet and supplementation (e.g., flavonoids) on BDNF-mediated brain functions." (PMID 25309465, 2014). "This is illustrated by a mice study showing sex differences in depressive behaviour in BDNF knock-out mice, in that male knock-out mice show normal levels of depression-like behaviour, whereas female knock-out mice display higher levels of depression-like behaviour." (PMID 24647525, 2014).
depression (continued). "Interestingly, BDNF genotype did moderate the mediating role of emotion focused coping in the relation between neglect and depression scores." (PMID 23824678, 2013). "Yet, there are still data that don't align nicely with a straightforward version of the BDNF hypothesis of depression." (PMID 23675319, 2013). "Indeed, results of several meta-analyses have established that BDNF levels are reduced in patients with depression, and that antidepressant medication seems to up-regulate their levels." (PMID 23286788, 2013). "Increasing clinical and experimental evidence indicated that BDNF played a role in the pathophysiology of depression and that antidepressants may in part exert their effects through regulation of BDNF." (PMID 23573124, 2013). "Although these studies indicate that BDNF might be a biomarker for depression, they don’t speak to the possibility that peripheral BDNF might actually contribute to this disorder." (PMID 23824678, 2013). "The 5-HT2A A-1438G, 5-HT2A T102C, BDNF Val66Met, and 5-HT1A C-1019G gene polymorphisms might predict the incidence of depression with ABB." (PMID 24274373, 2013). "Mental stress may inhibit the synthesis of brain-derived neurotrophic factor (BDNF) in the hippocampus which may be a contribution to the occurrence of depression." (PMID 24363618, 2013). "Recent studies suggest that chronic treatment with the SSRIs fluoxetine or sertraline increased hippocampal neurogenesis, ameliorated cognitive deficits, and depression-like behavioral symptoms in R6/1 mice and increased BDNF levels and neurogenesis in R6/2 mice." (PMID 23847583, 2013). "Whereas BDNF hyperactivity has been detected in epilepsy, autism and manic-depressive psychosis, a decreased activity of BDNF has been established in the hippocampus of patients with severe depression." (PMID 24300402, 2013). "This hypothesis links the changes in depression models to a decrease of brain-derived neurotrophic factor (BDNF) and the antidepressant effect to an increase in BDNF in hippocampus." (PMID 23862076, 2013). "In the next sections, the importance of adult neurogenesis and growth factors, especially BDNF, in relation to depression will be described and the potential interplay between pro-inflammatory cytokines and these factors in promoting depressive illnesses will be discussed." (PMID 23675319, 2013). "In summary, the present study demonstrated that the A-1438 and T102C polymorphisms of the 5-HT2A receptor gene, BDNF Val66Met, and 5-HT1A C-1019G might predict the incidence of depression induced by abnormal black bile." (PMID 24274373, 2013). "Interestingly, the BDNF genotype was found to moderate the mediating role of perception of control between neglect and depression scores." (PMID 23824678, 2013). "We therefore hypothesized that a genetic variation (Val to Met substitution) in BDNF leading to a reduction in serum BDNF levels in T2DM may contribute to depression and diabetes." (PMID 23968401, 2013). "There is increasing evidence that the BDNF might be one of the relevant factors in the pathophysiology of depression." (PMID 24274373, 2013). "Furthermore, we explored the roles of miR-132 and miR-182 on the BDNF levels in depression using human subjects by assessing their serum levels." (PMID 23704927, 2013). "We next studied the serum BDNF levels in patients with depression and controls by ELISA." (PMID 23704927, 2013). "The perspective that impairments of growth factor functioning, such as BDNF and others within the different families of growth factors, might contribute to major depression has gained increasing attention." (PMID 23675319, 2013). "Moreover, the decreased BDNF observed in heterozygous knock-out mice (BDNF+/−) is related to a depression-like phenotype." (PMID 23862076, 2013). "Our results demonstrate that the serum BDNF and its related miRNAs may be utilized as important biomarkers for the diagnosis or as the therapeutic targets of depression." (PMID 23704927, 2013).
depression (continued). "In this study, our results showed that the serum miR-132 levels were increased in patients with depression than those in controls, which might contribute to the lower serum BDNF levels." (PMID 23704927, 2013). "Additionally, in the animal model of depression, results demonstrate that antidepressant efficacy is mediated at least in part through an elevation of BDNF levels or BDNF-TrkB signaling in the hippocampus." (PMID 23573124, 2013). "Results of another study indicated a negative association between parietal-occipital alpha power in the eyes open resting state and depression severity estimated by the brain-derived neurotrophic factor as one of the important factors in the etiology of major depressive disorder." (PMID 24232245, 2013). "In contrast, a decrease in synaptic plasticity via inhibition of BDNF signaling following chronic stress could contribute to the cognitive deficits observed in those who score high on depression scales." (PMID 23641193, 2013). "In the present study, subjects carrying both 5-HT1A C1019G polymorphism CC genotype and Val/Val genotype of BDNF Val66Met polymorphism had over seven times higher risk of depression than those who did not have this combination of polymorphisms." (PMID 24274373, 2013). "Therefore, serum BDNF-related miRNAs, combined with serum BDNF levels, were investigated in this study to increase the feasibility of applying BDNF-related miRNAs in the diagnosis of depression." (PMID 23704927, 2013). "Additionally, the expression level of BDNF is also reported to be reduced in Parkinson’s disease (PD), depression, and stress." (PMID 23320097, 2013). "In addition, BDNF (and also NT3) produced antidepressant effect on behavioral models of depression which are abolished in mice deficient in TrkB receptor." (PMID 24222865, 2013). "Interestingly, reduced hippocampal volume in drug-free patients suffering from first-episode major depression was more pronounced among those with lower serum BDNF concentrations." (PMID 23675319, 2013). "In several studies, reduced serum BDNF levels in depression and reduced hippocampal BDNF expression in mouse models of affective disorders could be reversed by various antidepressant interventions." (PMID 23750220, 2013). "Altered BDNF signaling has been shown to involved in a variety of peripheral and central nervous system disorders, including dementia, amyotrophic lateral sclerosis, depression and schizophrenia, etc." (PMID 23967328, 2013). "Our results reported here in a Chinese population are in agreement with those reports such as BDNF may have a major role in the pathogenesis and treatment response of depression." (PMID 24274373, 2013). "BDNF is an important member of the neurotrophin family of growth factors, which induces stress in both animal models and human psychopathologies, including major depression, or posttraumatic stress disorder." (PMID 23704927, 2013). "Stress can significantly decrease protein expression levels of BDNF and its receptor TrkB and leads to atrophy of the brain limbic system structure (such as hippocampus and prefrontal cortex), finally inducing depression." (PMID 24367385, 2013). "The obtained evidence supports the hypothesis on theinvolvement of BDNF in the pathogenesis of various depression conditions, thusopening prospects for searching for new original antidepressants." (PMID 24455189, 2013). "The results also suggested that nobiletin counteracted the ability of CUMS to induce depression-like behavior in rats and might involve maintenance of hippocampal BDNF-TrkB pathway." (PMID 23573124, 2013). "Thus, this is a common molecular pathology that the disease shares with depression, and one which, along with the target gene BDNF is likely to mediate the deficits in hippocampal neurogenesis which is the cellular consistently observed in animal models of HD." (PMID 23847583, 2013).
depression (continued). "Considering the important roles of BDNF and miRNAs in the pathogenesis of depression, our current study was aimed at identifying the novel miRNAs that regulate serum BDNF levels, and characterizing the relationship between miRNAs and depression." (PMID 23704927, 2013). "Brain-derived neurotrophic factor (BDNF), a member of the neurotrophin family, plays critical roles in cell differentiation, neuronal survival, migration, and synaptic plasticity and has been implicated in the pathophysiology of depression." (PMID 23737815, 2013). "Most of the research on the implication of growth factors in depressive illnesses has concerned BDNF, although increasing efforts are now being devoted to examine the role of additional growth factors in depression and/or their contribution to the positive outcomes of antidepressants." (PMID 23675319, 2013). "Moreover, basal serum levels of sIL-2r and of IL-1ra predicted BDNF reductions during IFN-α therapy, but the two systems were independently associated with the development of depression during treatment." (PMID 23675319, 2013). "The role of hippocampal BDNF and subsequent neurogenesis in depression and in the therapeutic action of antidepressants is an emerging hypothesis, which is supported by many experimental data." (PMID 23805233, 2013). "The mediating role of coping styles in the relation between childhood neglect (predictor) and depression scores (outcome) was examined along with whether these relationships were moderated by BDNF genotype." (PMID 23824678, 2013). "Collectively, these results demonstrated that Xiangshao granule could effectively induce antidepressive effects in the depression mouse model by ameliorating the expression of hippocampal BDNF and TrkB." (PMID 24367385, 2013). "Either there's less to this hypothesis than initially meets the eye, or, more probably, there are moderating factors that determine whether, and under what circumstances, BDNF might be aligned with depression." (PMID 23675319, 2013). "By contrast, when chronic fluoxetine administration occurred in a stressful condition, mice showed a more distinct worsening of the depression-like profile, displaying a faster decrease of saccharin preference, lower brain BDNF levels and increased corticosterone levels." (PMID 23653679, 2013). "Furthermore, several lines of evidence suggest that acupuncture or EA can upregulate hippocampal BDNF expression in normal and depression model rats." (PMID 23737815, 2013). "However, despite the considerable interest in BDNF as a potential contributor to the evolution of depression secondary to stressful events, it seems that this relationship is not always straightforward." (PMID 23675319, 2013). "Similarly, we found that serum BDNF levels were lower in patients with depression compared with controls." (PMID 23704927, 2013). "BDNF was found to improve anxiety and depression characteristics across different tasks." (PMID 25226879, 2013). "After adjusting for those conventional depression risk factors such as age, gender, the AA (of the A-1438G polymorphisms of the 5-HT2A gene), Val/Val (of the Val66Met polymorphisms of the BDNF gene), CC (of the C-1019G polymorphisms of the 5-HT1A gene) genotype still had an approximately." (PMID 24274373, 2013). "Numerous studies have identified a key role of BDNF in the development and treatment of depression." (PMID 23737815, 2013). "Collectively, our study demonstrates that Xiangshao granule has a significant antidepressant effect in the mouse depression model with its desired therapeutic effect possibly achieved through increasing hippocampal BDNF and TrkB expression and downregulating serum CRH, CORT, and ACTH levels." (PMID 24367385, 2013). "Collectively, the decreased BDNF may be a pathogenetic factor involved not only in depression, but also in T2DM." (PMID 23968401, 2013). "In addition, we found a reverse relationship between the serum BDNF levels and the miR-132/miR-182 levels in depression." (PMID 23704927, 2013).
depression (continued). "Evidence indicates that BDNF could play a role in this association: i) in animal studies BDNF levels decreased after chronic stress, ii) serum BDNF levels decreased in stress-related major depressive disorder, iii) BDNF plays a role in sleep homeostasis." (PMID 24146812, 2013). "Furthermore, an up-regulation of BDNF mRNA expression following DOR activation has been reported in animal models of depression." (PMID 23912236, 2013). "Notably, it is possible that alteration in the expression and/or function of BDNF in the central nervous system is involved in the pathophysiology of various brain diseases, including depression." (PMID 26019865, 2013). "Another interesting finding in this study was that the development of depression-like phenotypes after prenatal exposure to a supra-therapeutic dose of buprenorphine was accompanied by decreased circulating levels of BDNF and serotonin, TrkB phosphorylation, and CREB activity." (PMID 24367510, 2013). "Secondary measures are diagnosis of PTSD and major depressive disorder, depressive symptoms, physiologic response in the experiment using script-driven imagery and acoustic stimulation, serum brain-derived neurotrophic factor, health-related quality of life, resilience, and aggression." (PMID 23289548, 2013). "BDNF is formed from cleavage of its precursor, proBDNF, a biologically active intermediate that may contribute to long-term depression and other effects counter to those of BDNF." (PMID 23285257, 2012). "Interestingly, overexpression and underexpression of BDNF in different parts of the brain of mice impaired their learning and memory and precipitated depression-like behavior." (PMID 22265241, 2012). "Previously, we reported that serum levels of BDNF in antidepressant-naïve patients with MDD were significantly lower than those of medicated patients and healthy controls, and that serum levels of BDNF were correlated negatively with the severity of depression." (PMID 22880079, 2012). "Therefore, BDNF is regarded as a promising target for studying pathophysiological processes in depression and for developing new antidepressant drugs." (PMID 22581450, 2012). "Additional evidence connecting BDNF and depression comes from studies showing that infusion of recombinant BDNF into the mouse midbrain or hippocampus produces an antidepressant effect in both learned helplessness and forced swim models of depression." (PMID 21799699, 2012). "We suggest that plasma BDNF could potentially serve as a prognostic biomarker for depression, predicting clinical outcome." (PMID 22761741, 2012). "If clinicians are looking for another justification for statin use in depression they could refer to the actions of BDNF." (PMID 23204984, 2012). "Opposing influences of mBDNF and proBDNF on long-term potentiation and long-term depression might contribute to the dichotomy of BDNF actions on behaviors mediated by the brain stress and reward systems." (PMID 23304210, 2012). "Our altered BDNF-Ntrk2 pathway finding was evident at 24 hours post the last stress episode of the sub-chronic stress paradigm and is consistent with a molecular signature of depression." (PMID 23075086, 2012). "In addition, serum BDNF levels are correlated with the severity of depression, and serum BDNF levels in patients treated with antidepressants increase to levels found in healthy subjects." (PMID 22761741, 2012). "Using a model of depression induced by chronic stress, Tsankova and colleagues (2006) found that the levels of the BDNF exon IV and exon VI were reduced in the hippocampus and that this effect could be blocked by chronic antidepressant treatment." (PMID 23584115, 2012). "Indeed, Nestler and colleagues have demonstrated a crucial role for BDNF in the mesolimbic system for the development of depression-like behaviour." (PMID 23075086, 2012).